HDAC8 (histone deacetylase 8)
Description:
Histone deacetylase that catalyzes the deacetylation of lysine residues on the N-terminal part of the core histones (H2A, H2B, H3 and H4). Histone deacetylation gives a tag for epigenetic repression and plays an important role in transcriptional regulation, cell cycle progression and developmental events. Histone deacetylases act via the formation of large multiprotein complexes. Also involved in the deacetylation of cohesin complex protein SMC3 regulating release of cohesin complexes from chromatin. May play a role in smooth muscle cell contractility. In addition to protein deacetylase activity, also has protein-lysine deacylase activity: acts as a protein decrotonylase by mediating decrotonylation ((2E)-butenoyl) of histones.
Synonyms: HD8; HDACL1; CDA07; RPD3; KDAC8; CDLS5; MRXS6; WTS
Tractability: Small molecule: an approved drug acts on it; a structure with a bound ligand is known; a high-quality ligand is known; it has a high-quality binding pocket; it belongs to a druggable protein family. PROTAC: ubiquitination databases record sites on it; a small molecule that binds it is known. Other modalities: an approved drug acts on it.
Target class: Eraser; HDAC class I; Epigenetic regulator; Histone deacetylase
Chemical probes: FK228 (high quality), PD081430, PD134173, PD134174, YX968 (high quality), pandacostat
Gene: Protein-coding gene on chromosome X (72,329,516 to 72,573,101, reverse strand). Ensembl gene ENSG00000147099.
Subcellular location: Nucleus; Chromosome; Cytoplasm
Pathways (Reactome):
Cell Cycle: Resolution of Sister Chromatid Cohesion; Separation of Sister Chromatids
Disease: Constitutive Signaling by NOTCH1 HD+PEST Domain Mutants; Constitutive Signaling by NOTCH1 PEST Domain Mutants
Chromatin organization: HDACs deacetylate histones
Developmental Biology: Differentiation of naive CD4+ T cells to T helper 2 cells (Th2 cells)
Gene expression (Transcription): Notch-HLH transcription pathway
Signal Transduction: NOTCH1 Intracellular Domain Regulates Transcription
Gene Ontology:
Molecular function: histone deacetylase activity; histone deacetylase activity, hydrolytic mechanism; histone decrotonylase activity; Hsp70 protein binding; Hsp90 protein binding; protein binding; protein decrotonylase activity; protein lysine deacetylase activity; DNA-binding transcription factor binding
Biological process: mitotic sister chromatid cohesion; negative regulation of protein ubiquitination; regulation of protein stability; regulation of telomere maintenance; chromatin organization; heterochromatin formation; negative regulation of transcription by RNA polymerase II
Cellular component: chromosome; cytoplasm; nucleus; histone deacetylase complex; nuclear chromosome; nucleoplasm
Gene-disease validity (ClinGen):
ClinGen rates the evidence that HDAC8 causes each of these diseases.
Cornelia de Lange syndrome (X-linked): Definitive. A rare syndrome characterized by low birth weight, delayed growth, intellectual disabillity, behavioral problems, and a distinctive facial appearance (thin, arched eyebrows, low set ears, small teeth, and small nose).
Homologues: Orthologues: dog HDAC8 (98% identical), macaque CITED1 (98% identical), mouse Hdac8 (96% identical), rat Hdac8 (95% identical), guinea pig HDAC8 (94% identical), rabbit HDAC8 (93% identical), chimpanzee HDAC8 (90% identical), pig HDAC8 (89% identical), tropical clawed frog hdac8 (79% identical), zebrafish hdac8 (73% identical), Caenorhabditis elegans F43G6.4 (11% identical), Caenorhabditis elegans hda-5 (7% identical), and 1 more. Paralogues in human: HDAC1 (42% identical), HDAC2 (42% identical), HDAC3 (40% identical), HDAC4 (27% identical), HDAC7 (26% identical), HDAC9 (26% identical), HDAC5 (26% identical), HDAC6 (25% identical), HDAC11 (16% identical), HDAC10 (11% identical).
Diseases named in the same sentence as HDAC8 in open-access papers:
HDAC8 is named in the same sentence as 167 diseases in open-access papers, as found by Europe PMC text mining. Sharing a sentence is not in itself a finding about the gene and the disease. The quoted sentences say what the papers report.
Cornelia de Lange syndrome (62 papers, 2013 to 2025). "It is, however, well established that HDAC8 mutations in humans affecting its deacetylase activity can cause subtypes of Cornelia de Lange syndrome, a genetic developmental disorder affecting multiple functions." (PMID 39779705, 2025). "Pathogenic variants in NIPBL, MAU2, SMC1A, SMC3, RAD21, and HDAC8 cause Cornelia de Lange syndrome (CdLS), a multisystem disorder characterized by intellectual disability, facial dysmorphism, growth delay, and upper limb anomalies." (PMID 41492387, 2025). "The boy presented with a diaphragmatic hernia, a rare abnormality in Cornelia de Lange syndrome (CdLS), suggesting a potential need for further investigation of its association with variants in the HDAC8 gene." (PMID 38673696, 2024). "HDAC8 is the causative gene for Cornelia de Lange syndrome (CdLS), a genetically heterogeneous disease entity with characteristic facial features, developmental delay, and other neurologic features." (PMID 37645600, 2023). "By contrast, missense and LoF variants in the other X-linked gene involved in Cornelia de Lange syndrome, HDAC8, resulted in severely affected males with either healthy or mildly affected carrier mothers." (PMID 35887945, 2022). "In humans, loss-of-function HDAC8 mutations cause Cornelia de Lange syndrome with multisystem genetic disorders." (PMID 33959033, 2021). "The other is HDAC8, which is associated with Cornelia de Lange syndrome (CDLS5), a developmental disorder characterized by short stature and intellectual disability with variable clinical presentations." (PMID 34069769, 2021). "The proband’s clinical features were consistent with the clinical diagnosis of Cornelia de Lange syndrome, a clinical and genetically heterogeneous disorder, caused by heterozygous pathogenic variants in HDAC8 among others." (PMID 29293505, 2018). "Mutations in HDAC8 are associated with Cornelia de Lange syndrome, a dominantly inherited congenital disorder." (PMID 29100057, 2017). "Mutations in HDAC8 cause Cornelia de Lange syndrome, a developmental disorder characterized by facial dysmorphology including hypertelorism." (PMID 27560520, 2016). "SMC3, a subunit of the cohesin complex, is a widely recognized HDAC8 substrate involved in entrapment of sister chromatids and genome maintenance, of which dysregulated acetylation has been linked to Cornelia de Lange syndrome, a genetic disorder that affects many organs." (PMID 39436709, 2024). "In that study we suggested that the relevant gene might be HDAC8, which is associated with Cornelia de Lange syndrome–a condition characterized by hypertelorism." (PMID 28441456, 2017). "Overexpression of HDAC8 has been associated with cell proliferation of multiple cancer cells; whereas, defective mutations of HDAC8 are linked to Cornelia de Lange syndrome, which is a rare genetic disease manifesting congenital malformations of multiple organs due to defects in cohesin." (PMID 28509866, 2017). "Mutations in NIPBL, cohesin, and its deacetylase HDAC8 result in Cornelia de Lange syndrome." (PMID 26725122, 2016). "Causal variants of HDAC8 have been reported in individuals with Cornelia de Lange Syndrome (CdLS) and in a family with X-linked intellectual disability." (PMID 38473789, 2024). "The class I deacetylase HDAC8 deacetylates cohesin, and the enzyme is implicated in Cornelia de Lange syndrome (CdLS)." (PMID 26598605, 2016). "Mutations in core cohesin subunits SMC1A, SMC3 and RAD21, or their regulators NIPBL and HDAC8, cause Cornelia de Lange syndrome (CdLS)." (PMID 26581180, 2015). "The most common cohesinopathy, Cornelia de Lange syndrome, is caused by dysfunction in a variety of cohesin subunits, such as NIPBL, SMC1A, SMC3, RAD21, BRD4, HDAC8, and ANKRD11." (PMID 40943870, 2025).
Cornelia de Lange syndrome (continued). "Increased expression of HDAC8 is associated with cell proliferation in various cancer cells, whereas mutations in the HDAC8 gene have been linked to Cornelia de Lange syndrome (CdLS), which is a rare, genetically heterogeneous disorder that affects multiple organs and systems." (PMID 39043961, 2024). "Cornelia de Lange syndrome (CdLS) has seven disease-associated genes; two of them localize (SMC1A and SMC3) to cilia and two of them (ANKRD11 and HDAC8) are implicated in cilia." (PMID 37542408, 2023). "The most famous among them is the Cornelia de Lange Syndrome (CdLS), which is an autosomal dominant (NIPBL, SMC3, RAD21) and X-linked (SMC1 and HDAC8) disease with almost complete penetrance." (PMID 35222432, 2022). "HDAC8 expression is involved in various diseases including Cornelia de Lange syndrome (CdLS), viral infections, schistosomiasis, and cancer." (PMID 35955780, 2022). "The major causative genes of the Cornelia de Lange Syndrome are NIPBL, SMC1A, SMC3, RAD21 and HDAC8." (PMID 34827619, 2021). "Therefore, mutations of HDAC8 result in the Cornelia de Lange syndrome (CdLS), a dominantly inherited congenital malformation disorder." (PMID 34435400, 2021). "Cornelia de Lange syndrome (CdLS) results from autosomal dominant or X-linked mutations in NIPBL, SMC1A, SMC3, RAD21 or HDAC8." (PMID 31935221, 2020). "Cornelia de Lange syndrome (CdLS), the best characterized cohesinopathy, is caused by mutations of cohesin regulators, such as NIPBL and HDAC8, or of cohesin subunits, including SMC1A, SMC3, and RAD21." (PMID 33262685, 2020). "Cornelia de Lange syndrome (CdLS), a rare, multisystemic disorder, has been linked to genetic alterations in NIPBL, SMC1A, SMC3, HDAC8, and RAD21 genes." (PMID 30606125, 2019). "The second class is Cornelia de Lange Syndrome, which can be caused with varying degrees of severity by pathogenic mutations in NIPBL (CdLS1), SMC1 (CdLS2), SMC3 (CdLS3), SCC1 (CdLS4), and HDAC8 (CdLS5)." (PMID 29263825, 2017). "This study provides insight into the molecular pathology of Cornelia de Lange syndrome by establishing a relationship between NIPBL and HDAC8 mutations and PKR activation." (PMID 26725122, 2016). "Nevertheless, one of the three de novo nonsynonymous mutations (c.356C>T [p.Thr119Met]) identified by Diamund was in HDAC8 (MIM #300269), one of the genes known to cause Cornelia de Lange syndrome 5 (MIM #300882)." (PMID 24375697, 2014). "For example, one proband had two pathogenic de novo variants in genes linked with two distinct conditions, resulting in seven phenotypes attributable to HDAC8 (Cornelia de Lange syndrome [MIM: 300882]) and just one attributable to PAX8 (congenital hypothyroidism [MIM: 218700])." (PMID 39353430, 2024). "Growth retardation, craniofacial anomalies, microbrachycephaly and reduced body fat have been described in cohesinopathies such as Cornelia de Lange syndrome CdLS, which is inherited in an autosomal dominant (NIPBL, SMC2 or RAD21) or X‐linked (SMC1A or HDAC8) pattern." (PMID 36627765, 2023). "However, to our knowledge, this is the first published case of HDAC8‐related Cornelia de Lange syndrome with intestinal malrotation." (PMID 30632303, 2019). "Because WDSTS can phenotypic overlap with Pierpont syndrome, Cornelia De Lange syndrome and Kabuki syndrome, the candidate genes causing the later three syndromes (i.e. TBL1XR1, NIPBL, SMC1A, SMC3, RAD21, HDAC8, KMT2D, and KMD6A) in our cohort have been excluded." (PMID 30305169, 2018). "Mutation of HDAC8 results in increased SMC3 acetylation level and inefficient dissolution of cohesin complex released from chromatin in prophase and anaphase during the cell cycle, leading to Cornelia de Lange syndrome (CdLS)." (PMID 28223544, 2017). "HDAC8 was recently shown to deacetylate SMC3, with loss-of-function HDAC8 mutations showing impaired cohesin complex regulation and being linked to the congenital malformation disorder, Cornelia de Lange syndrome." (PMID 23752268, 2013).
Cornelia de Lange syndrome (continued). "HDAC8 is also associated with the development of non-cancer diseases such as Cornelia de Lange Syndrome (CdLS), infectious diseases, cardiovascular diseases, pulmonary diseases, and myopathy." (PMID 36231123, 2022). "Variants in genes encoding various structural or functional components of the cohesin complex, including RAD21, SMC1A, SMC3, BRD4, STAG1/2, NIPBL, HDAC8, WAPL, ANKRD11 and in single individuals PDS5A and ESPL1, have been implicated in Cornelia de Lange Syndrome (CdLS)." (PMID 32193685, 2020). "Genetic alterations of NIPBL, SMC1A, SMC3, HDAC8, and RAD21 genes are believed to trigger the development of Cornelia de Lange syndrome." (PMID 30606125, 2019). "Cornelia de Lange Syndrome (CdLS) is a genetically heterogeneous disorder predominantly caused by De Novo heterozygous pathogenic variants in NIPBL (80% of cases), with less frequent involvement of SMC1A (5%), HDAC8 (4%), SMC3 (1–2%), RAD21 (<1%), and BRD4 (<1%)." (PMID 40700109, 2025). "Cornelia de Lange syndrome (CdLS, OMIM # 122470, #614701, #610759, #300590, and #300882) is a rare genetic disorder caused by variants in cohesion complex genes including NIPBL (NM_133433.3), SMC1A (NM_006304.4), SMC3 (NM_005445.3), HDAC8 (NM_018486.2), and RAD21 (NM_006265.3)." (PMID 35935361, 2022). "However, after conducting whole exome sequencing analysis, no genetic variants associated with Cornelia de Lange syndrome, such as NIPBL, SMC1A, SMC3, RAD21 and HDAC8 were found." (PMID 38348454, 2024).
neuroblastoma (40 papers, 2012 to 2026). Neuroblastoma (NB) is the most common solid, extracranial childhood tumor. "In childhood neuroblastoma, upregulation of HDAC8 was associated with advanced stage, poor prognosis, and poor survival." (PMID 39063083, 2024). "HDAC8 is a key regulator of cancer cell differentiation, and HDAC8 overexpression is associated with neuroblastoma progression." (PMID 35458763, 2022). "Of specific interests are Class I HDAC isozymes, HDAC2 and HDAC8, which are important targets in cancer models as both are associated with high risk diseases such as prostate cancer and neuroblastoma." (PMID 32318119, 2020). "HDAC8 is upregulated in breast cancer, urothelial cancer, hepatocarcinoma, and acute lymphatic leukemia, and is associated with poor prognosis and low overall survival rates in neuroblastoma." (PMID 35955780, 2022). "From a clinical perspective, combination of HDAC8 inhibition with retinoic acid treatment might be a promising strategy in the maintenance treatment of high-risk neuroblastoma." (PMID 25695609, 2015). "Moreover, increased expression of HDAC8 is associated with poor outcomes in neuroblastoma." (PMID 38473789, 2024). "Especially, HDAC8 expression is positively correlated with advanced-stage diseases and poor outcomes in neuroblastoma and breast cancer (BC)." (PMID 36231123, 2022). "HDAC8 inhibition is correlated to the block of cell proliferation, the induction of cell cycle arrest and the promotion of differentiation in neuroblastoma cell line." (PMID 36077415, 2022). "The combination of in vitro screening and cellular testing demonstrated selective HDAC8 PROTACs that show anti-neuroblastoma activity in cells." (PMID 35886887, 2022). "HDAC8 overexpression was reported in neuroblastoma, whereas low HDAC4 levels are reported in gastric cancers." (PMID 35458763, 2022). "In particular, in neuroblastoma, the HDAC-8 appears to correlate with poor prognosis, and many attempts were made to inhibit its function." (PMID 36139583, 2022). "The specific inhibitors 1-naphthohydroxamic acid (Cpd2) and PCI-34051, for example, showed potential HDAC-8 inhibitory activity and thereby decreased the neuroblastoma cell viability." (PMID 36139583, 2022). "As shown in several studies, HDAC8 can be considered a potential target in the treatment of cancer forms such as childhood neuroblastoma." (PMID 35886887, 2022). "Within this study, we investigated the HDAC8-degrading profiles of the synthesized PROTACs and their effect on the proliferation of neuroblastoma cells." (PMID 35886887, 2022). "Histone deacetylase 8 (HDAC8) was overexpressed in metastasized stage 4 neuroblastomas, which correlated with poor prognosis in addition to stage 4S disease." (PMID 35454815, 2022). "HDAC8 inhibition using siRNA upregulates miR-137 which increases Dox sensitivity in neuroblastoma cells by reducing the expression of constitutive androstane receptor and its target, multidrug resistance protein 1 (MDR1)." (PMID 36231123, 2022). "In neuroblastoma, HDAC8 is the only enzyme among 11 HDAC isoforms (HDAC1-11) that significantly correlates with the advanced stage." (PMID 36231123, 2022). "HDAC8 is overexpressed in diverse cancer tissues, including colon, breast, lung, pancreatic, and liver cancers and childhood neuroblastoma." (PMID 34395273, 2021). "Increased expression of HDAC1, 2 and 3 has been associated with poor outcome in gastric and ovarian cancer, while high HDAC8 levels correlate with advanced disease and poor survival in neuroblastoma." (PMID 34654445, 2021). "HDAC8 is also upregulated in neuroblastoma, a childhood pediatric cancer, hence considered a drug target for this cancer subtype." (PMID 32318119, 2020). "The results of this study lay the foundation for future design strategies toward more potent HDACis for HDAC8 isozymes and further therapeutic applications for neuroblastoma." (PMID 32318119, 2020).